NOS2 (nitric oxide synthase 2)
Diseases named in the same sentence as NOS2 in open-access papers (continued):
Sharing a sentence is not in itself a finding about the gene and the disease.
Insulin resistance (20 papers, 2013 to 2026). Increased resistance towards insulin, that is, diminished effectiveness of insulin in reducing blood glucose levels. "Together with the predicted upregulation of Adipoq, Pparg and Ppargc1a and downregulation of Nos2 nodes, the overall transcriptome shift corresponds to a gene expression profile repeatedly associated with amelioration of insulin resistance." (PMID 36245490, 2022). "NOS3 is associated with anti-obesogenic effects, while NOS2 promotes insulin resistance." (PMID 37371984, 2023). "In turn, in insulin resistance, NOS2 participates in the deregulation of metabolic processes in tissues by disturbing glucose and lipid homeostasis and causing endothelial dysfunction through the local and systemic formation of an inflammatory environment." (PMID 39061907, 2024). "Under conditions of metabolic stress, lipid accumulation in NOS2-/- rat maybe develop into a variety of metabolic syndrome, such as insulin resistance, type 2 diabetes, vascular pathology and hepatic steatosis." (PMID 33816486, 2021). "However, it is known that in the states of insulin resistance, NOS2 participates in the deregulation of metabolic processes of tissues by disturbing the balance in glucose and lipid homeostasis and endothelial dysfunction through the creation of local and systemic inflammatory environments." (PMID 33374571, 2020). "Pro‐inflammatory macrophages, characterized by elevated expression of CD11c+ and Nos2, secrete inflammatory cytokines such as TNF‐α, IL‐6, and IL‐1β, thereby inhibiting GLUT4 expression and worsening insulin resistance." (PMID 41509193, 2026).
malaria (20 papers, 2008 to 2021). Malaria is a serious and sometimes fatal disease caused by a parasite that commonly infects a certain type of mosquito which feeds on humans. "The only variant that showed significant influence on malaria incidence was the NOS2 −954 G>C (rs 1800482) promoter variant." (PMID 28793894, 2017). "Other host polymorphisms within the inducible nitric oxide synthase 2 (NOS2) gene promoter also appear to be protective against severe malaria and uncomplicated malaria." (PMID 28793894, 2017). "Inducible nitric oxide synthase 2 (NOS2 −954 G>C; rs 1800482) heterozygosity was associated with lower incidence of malaria in all age groups {Adjusted incident rates ratio (aIRR) 0.59; 95% CI [0.386–0.887]; P = 0.012)}." (PMID 28793894, 2017). "Independent of age, the most significant effect observed in this study was the heterozygous NOS2 −954 G>C mutation, which showed a lower incidence of uncomplicated malaria." (PMID 28793894, 2017). "The production of NO and the cellular expression of enzyme-inducible nitric oxide synthase (NOS2) are associated with protection against severe forms of malaria." (PMID 23316245, 2012). "However, it is noteworthy that other genetic modifiers of malaria susceptibility, namely NOS2, act as downstream effectors of TNF signaling encouraging further investigations on the intertwining of TNF and nitric oxide in disease development." (PMID 31417551, 2019). "In other studies, NOS2 −954 G>C polymorphism heterozygosity was associated with protection against severe malaria, yet else where, no relation between NOS2 polymorphisms and susceptibility to malaria or asymptomatic malaria was observed." (PMID 28793894, 2017). "In previous studies, increased levels of nitric oxide were shown to be important in parasite clearance and protection against P. falciparum infection, yet few studies have investigated the relationship between NOS2 polymorphisms and the incidence of uncomplicated malaria." (PMID 28793894, 2017). "In turn, the known SNP marker −51T→C within the core-promoter of the human NOS2 gene (inducible nitric oxide synthase 2) exemplifies the so-called balanced SNPs, which can have both beneficial (malaria resistance) and adverse effects (epilepsy risk) on human health." (PMID 26516624, 2015). "Several polymorphisms in the NOS2 gene have been associated with malaria severity." (PMID 23316245, 2012). "We revisited genetic evidence provided by inflammatory response genes that have been repeatedly associated to malaria, namely TNF, NOS2, IFNAR1, HMOX1, TLRs, CD36, and CD40LG." (PMID 31417551, 2019). "In the present study, the associations between the incidence of uncomplicated malaria and HBB, G6PD and NOS2 gene polymorphisms were determined in a 1 year follow up study." (PMID 28793894, 2017). "An earlier study that was done in Kampala, Uganda showed reduction in the incidence of mild malaria among NOS2 −954 G>C heterozygotes." (PMID 28793894, 2017). "The purpose of the current study was to determine the relationship of blood monocyte activation to hypoargininemia and low NO/NOS2 in Tanzanian children with malaria." (PMID 27385484, 2016). "Our prior studies of NO in malaria have focused on NOS2 (inducible NOS), which is expressed in multiple tissues, including brain and endothelium." (PMID 25764173, 2015). "The study confirms the known protective effect of HbS against severe malaria and also reveals a protective effect of SNPs in the nitrogen oxide synthase 2 (NOS2) gene against malaria infection, anaemia and uncomplicated malaria." (PMID 24934404, 2014). "One particular study from Uganda associated the NOS2 −954 G>C, but not the −1173 C>T promoter polymorphism (rs 9282799) with reduced malaria incidence rates." (PMID 28793894, 2017). "On analysis, NOS2 −954 G>C heterozygotes had significantly lower malaria incidence rates as compared to those without the mutation (aIRR = 0.59; 95% CI [0.386–0.887]; P = 0.012)." (PMID 28793894, 2017).
malaria (continued). "The frequencies of HBB, G6PD, and NOS2 polymorphisms of children lacking malaria symptoms throughout the year and those showing malaria symptoms were statistically similar." (PMID 28793894, 2017). "Our data demonstrate that there is an M2-like activation monocyte phenotype in children with falciparum malaria, with high monocyte counts and plasma arginase levels, low arginine levels, and low monocyte NOS2, forming an important basis of the low NO bioavailability observed in malaria." (PMID 27385484, 2016). "PBMC arginase 1 mRNA was markedly elevated and NOS2 lower in children with malaria." (PMID 27385484, 2016). "While we have established that there are multiple mechanisms by which NO bioavailability is limited in malaria, we do not fully understand the underlying processes leading to NO bioinsufficiency and, in particular the impairment of NOS2 expression in severe malaria." (PMID 27385484, 2016). "It further provides the first evidence that polymorphisms in NOS2 and EMR1 may be associated with mild malaria, G6PD with anaemia while SNPs in ADCY9 and EMR1 may be linked with severe malaria in the Cameroonian population." (PMID 24934404, 2014). "Another SNP in NOS2, −1173C>T (no rs designation available), was associated with protection against cerebral malaria in children in Tanzania and severe anemia in malaria individuals of Kenya." (PMID 23316245, 2012). "The protective effects of NOS2 variants have not been consistently observed in different studies possibly owing to differences in the genetic variants analyzed, in the ethnic groups studied or in regional epidemiologic patterns of clinical malaria." (PMID 31417551, 2019). "Although the CCTTT pentanucleotide microsatellite repeat in iNOS promoter is thought to play a key role in the pathogenesis of severe malaria, the protective effects for NOS2 SNP is quite interesting since, no previous associations between rs2297518 and malaria have been reported." (PMID 24934404, 2014). "Severe falciparum malaria is associated with low NO bioavailability, and a polymorphism in the nitric oxide synthase 2 (NOS2) promoter—which increases NO production and is prevalent in Kenyan and Tanzanian children—was associated with substantial protection from severe malaria." (PMID 23696730, 2013). "Mechanisms which may decrease endothelial NO bioavailability in severe malaria include impaired nitric oxide synthase 2 (NOS2) expression, hypoargininemia, quenching by cell-free haemoglobin, and increased concentrations of the nitric oxide synthase inhibitor, asymmetrical dimethylarginine (ADMA)." (PMID 23922746, 2013). "However, in Tanzania, neither NOS2 −954G>C polymorphisms nor CCTTT repeats were associated with severe malaria." (PMID 23316245, 2012). "Here we investigated a possible influence of this deletion in malaria and hepatitis C. There is evidence that IFN-α can induce NOS2 expression and NO production by human mononuclear cells in vitro and in vivo." (PMID 19055755, 2008). "Despite that accumulated knowledge, investigators have not been able to fully understand the basis of the low NOS2 levels and NO production in malaria." (PMID 27385484, 2016). "In Gambia, the SNP NOS2 −954G> C (no rs designation available) has been associated with resistance to severe malaria, whereas in another group of Gambian subjects, short forms of the polymorphic microsatellite (CCTTT) in the NOS2 transcription start site were associated with fatal malaria." (PMID 23316245, 2012).
Stroke (19 papers, 2016 to 2025). Sudden impairment of blood flow to a part of the brain due to occlusion or rupture of an artery to the brain. "We detected that the G/G genotype and G allele of the c.-227G > C—NOS2 SNP were associated with a decreased occurrence of a stroke (bootstrap crude ORs 0.69; 0.51–0.94 95% CI; SP 0.710 and 0.77; 0.63–0.93; SP 560, respectively)." (PMID 33808851, 2021). "In the present study, we have additionally investigated, the prevalence of two SNPs in NOS2 gene (c.1823C > T; rs2297518) and c.-227G > C; rs10459953), and the association between these genetic polymorphisms and stroke risk." (PMID 33808851, 2021). "In this study, we also investigated the association between the occurrence of stroke and haplotypes of the c.1823C > T and the c.-227G > C polymorphisms of the NOS2 gene." (PMID 33808851, 2021). "The c.-227G > C (rs10459953) polymorphism in the NOS2 gene and stroke risk." (PMID 33808851, 2021). "The c.1823C > T (rs2297518) polymorphism in the NOS2 gene and stroke risk." (PMID 33808851, 2021). "We hypothesize that single nucleotide polymorphisms (SNPs) in the SOD2, CAT, GPX4, NOS1 and NOS2 genes might be associated with altered susceptibility to oxidative stress and stroke development." (PMID 33808851, 2021). "In conclusion, our results showed that the genetics variants in the SOD2 (c.47T > C; rs4880), GPX4 (c.660T > A; rs713041), NOS1 (g.117803515C > T; rs1879417) and NOS2 (c.1823C > T; rs2297518 and c.-227G > C; rs10459953) genes may be associated with individual susceptibility to a stroke." (PMID 33808851, 2021). "The data show miR-122 mimic given at 0 and 6 h improves stroke outcome possibly by the combined knockdown of NOS2 in BMVECs in the current study and with knockdown of NOS2 in leucocytes in our previous study." (PMID 30405345, 2018). "Since we have previously shown that miR-122 mimic decreases NOS2 expression in blood leucocytes after stroke, this study was designed to show that miR-122 mimic also decreases NOS2 expression in BMVECs." (PMID 30405345, 2018). "Numerous polymorphisms, occurring within this gene [especially g.117803515 C > T—NOS1 (rs1879417) and c.1823C > T—NOS2 (rs2297518)], play an essential role in the development mechanism of various diseases, including Fanconi anemia, depression, stroke, gastric, and urinary bladder cancer." (PMID 35732787, 2022). "Post-ischemic NOS2 is expressed in leukocytes and brain endothelial cells of rodents and humans, though decreasing NOS2 expression in leucocytes alone is insufficient to improve stroke outcomes." (PMID 30405345, 2018). "Since NOS2 is a key player in the post-ischemic inflammatory cascade, and inhibiting NOS2 has an extended therapeutic window out to at least 6 h, it suggests that miR-122 mimic could have a broad therapeutic window to treat stroke." (PMID 30405345, 2018). "The important biological targets for network pharmacological analysis of TM-CX and TM-JH related to stroke were PTGS2, ACE, APP, NOS1, and NOS2." (PMID 32328128, 2020). "Nitric oxide synthase 2 (NOS2), which also appeared in Module 195, was the target of triflusal, which was used to prevent cardiovascular events such as stroke." (PMID 29403392, 2018). "Triflusal, a treatment for stroke re-occurrence, targets four genes (PTGS1 (also known as Cox-1), NOS2, NFKB1, and PDE10A) that together have more functional variants in the African population than in any other population (DRPAFR = 37%)." (PMID 29273096, 2017). "Gene expression of the proinflammatory M1 microglia marker Stat3 was significantly increased in NT stroke vs NT Sham (P < 0.05), whereas expression of Tnfa and Nos2 were not changed." (PMID 38886874, 2024). "Although the pro-inflammatory NOS2 expression in the peri-infarct cortex is increased in all stroke mice, the mice lacking CCR5 in the brain and/or bone marrow display increased expression of NOS2." (PMID 33532129, 2021).
Stroke (continued). "Moreover, we show that miR-122 does not bind to the 3′UTR of NOS2, suggesting it may improve stroke outcomes in part by indirect inhibition of NOS2." (PMID 30405345, 2018). "In hippocampal tissues, mRNA expression studies at 1 h and 24 h, and strongly elevated (Egr1, Akt1, Kras, Src, Foxo, Srf, Vegfr2, Nos3, Nos1) and decreased (Nos2, Nfkb) gene expression (Mapk1 not activated) also support BPC 157 beneficial effect on brain lesions, given in reperfusion in stroke-rats." (PMID 34203464, 2021).
gastric cancer (18 papers, 2010 to 2025). A primary or metastatic malignant neoplasm involving the stomach. "Data confirmed that there was a sufficiently high amount of ARG1 and NOS2 to cause T cell function inhibition in HLA-DR-/low mononuclear cells under gastric cancer conditions." (PMID 32415175, 2020). "Polymorphism NOS2 -954 G/C, along with alcohol intake and tobacco smoking, is associated with gastric cancer." (PMID 20565800, 2010). "Multivariate logistic regression showed that the NOS2 SNP -954G/C was associated with higher risk of gastric cancer (OR = 1.87; 95% CI = 1.12-3.13)." (PMID 20565800, 2010). "In gastric cancer, the increase of NOS2 expression correlates with the decrease of survival rate and disease stage.What’s more, the expression of NOS2 is associated with metastasis of gastric cancer and the increase of angiogenesis." (PMID 37144125, 2023). "Therefore, in the present study, we investigated whether NOS2 polymorphisms affect the risk of developing gastric cancer and chronic gastritis in a Brazilian population." (PMID 20565800, 2010). "In summary, high NO/NOS2 levels serve as markers of poor prognosis in pancreatic, colorectal, hepatocellular, glioblastoma, and, to a lesser extent, gastric cancers." (PMID 40642105, 2025). "We confirmed, on a larger set of samples, our previous observation that NOS2 upregulation is greater in cardia subtype of gastric cancer." (PMID 34439753, 2021). "The compounds with high recommendation value in the network mainly have the highest acacetin, wogonin, baicalein, Salvigenin, and Moslosooflavone value ranking of gastric cancer disease-related targets mainly NOS2, PTGS1, PTGS2, DPP4, and so on." (PMID 34421596, 2021). "We conducted a population-based case-control study in 474 Southeast Brazilian individuals (150 with gastric cancer, 160 with chronic gastritis, and 164 healthy individuals), in which we performed NOS2 genotyping by PCR-RFLP." (PMID 20565800, 2010). "In gastric cancer, the prognostic role of NOS2 is less consistent but notable in advanced cases." (PMID 40642105, 2025). "For example, the M1 Macrophage marker NOS2 and the dendritic cell marker, HLA-DPB1 and CD1C, were significantly correlated with ARHGAP11A expression in gastric cancer." (PMID 34733886, 2021). "The inverse regulation of nitric oxide synthase 2 (NOS2) and ASL has been observed in gastric cancer and suggests arginine metabolism and nitric oxide production may be dysregulated in EED." (PMID 39300663, 2024).
Granuloma (18 papers, 2014 to 2025). A compact, organized collection of mature mononuclear phagocytes, which may be but is not necessarily accompanied by accessory features such as necrosis. "Previously, we have demonstrated that foamy macrophages in necrotizing granulomas express typical macrophage polarization markers, either Nos2 or Arg1, suggesting their differentiation into a pro-inflammatory or anti-inflammatory state." (PMID 40843005, 2025). "We also identify Trem2+ MΦs, which were recently identified as a MΦ subset in human M. leprae granulomas, as well as Nos2+ MΦs, a distinct MΦ phenotype in Mtb and S. enterica granulomas." (PMID 36608122, 2023). "Some Nos2–/– granulomas had single breaches in the macrophage zone, whereas other granulomas lost the macrophage zone altogether." (PMID 37865673, 2023). "We observed demarcated granulomas, similar to those observed after infection of Nos2−/− mice via the dermal route with viable M. tuberculosis." (PMID 29471332, 2018). "The expression of NOS2, NOS3 and nitrotyrosine (N-tyr) are all increased in the granuloma-associated inflammatory cells and in pneumonitis regions of human tuberculous lungs." (PMID 29085351, 2017). "In tuberculosis granulomas, arginase 1-expressing M2 macrophages localize to the outer regions of granulomas, while NOS2-expressing M1 macrophages can be found in the inner regions." (PMID 28223985, 2017). "Our spatial transcriptomics data provide gene expression patterns at single-cell resolution within cryptococcal granulomas and reveal highly heterogenous myeloid cells in the granuloma center, some of which appear highly interferon-responsive based on expression of Il1rn, Nos2 and Acod1." (PMID 40568097, 2025). "Nos2–/– mice had greater affected areas of the liver, and their granulomas were markedly abnormal." (PMID 37865673, 2023). "Previously, in our group, a C57BL/6J Nos2–/– mouse model presenting granuloma that includes central necrosis, hypoxia, and caseation has been established with an intradermal M. tuberculosis infection and transitory blocking of tumor necrosis factor alpha (TNF-α) function (37, –, 39)." (PMID 34311585, 2021). "However, it is important to note that the increased frequency of mature granulomas was directly accompanied by increased areas of NOS2 staining in the liver, which reflects the importance of IFN-γ in limiting the hepatic infection." (PMID 28775724, 2017). "The M1 (NOS2-positive) and M2 (CD168-positive) subpopulations were quantified in alveolar septa and granuloma for assessment of extension and severity." (PMID 28360865, 2017). "In contrast with these results, we did not observe a significant decrease in M1 marker genes, including MMP9, NOS2, CCL2, IL-6 and ARG2, in granuloma FCMs compared with NFMs, although MMP13 and NF-κB1 levels, which are also M1-related genes, were decreased." (PMID 26197235, 2015). "Granulomas in brucellosis have been shown to occur in various tissues and are of the epithelioid type, with CD11b+, F4/80+, MHCII+ cells expressing high levels of Nos2 in agreement with our findings." (PMID 25919005, 2014). "Regarding the upregulation of NOS2 in PBMCs, NOS2 is recognized as a marker of M1 macrophages, which exhibit pro-inflammatory functions induced by LPS or IFN-γ and also generate NO from L-arginine to prevent bacterial growth in inflammation sites including granulomas." (PMID 41463010, 2025).